FN1 (fibronectin 1)
Diseases named in the same sentence as FN1 in open-access papers (continued):
Sharing a sentence is not in itself a finding about the gene and the disease.
tumor (continued). "The levels of eight hub genes expression (FN1, CCND1, CDH2, CXCL12, MET, IRS1, DCN and FMOD) in PTC and para-cancerous non-tumor tissues were detected by qRT-PCR." (PMID 32714651, 2020). "To validate the results from RNAseq, we measured expression of six genes (COL1A1, FN1, MMP2, TFPI2, CDK6, and CDK4) that were significantly up-regulated in tumor cells compared to normal epithelium by RT-qPCR." (PMID 33142242, 2020). "Of note, FN1 is the only molecule overlapping in the gene matrices of the EMT score and CAF index, implying its essential role in tumor progression." (PMID 32605311, 2020). "Future relevant work may also include the determination of whether FN1 is acting via intracellular regulation of molecules on their way to the cell surface, or via the secretion and autocrine binding of FN1 to its own receptors or in a paracrine fashion affecting nearby tumor cells." (PMID 32630254, 2020). "To elucidate the origin of TGFBI, TNC, and FN1 in HGSC ascites, we made use of our transcriptome, proteome, and secretome datasets for tumor cells, TAMs, and TATs7,33." (PMID 32312959, 2020). "The joint score of FN1&POSTN expression appeared to be an independent prognostic factor in terms of OS, as well as residual tumor size, presence of angioinvasion, and necrosis." (PMID 31936272, 2020). "Using our recently established circulating tumor cell (CTC) lines, we had demonstrated increased FN1 expression and enhanced migration in CTC lines, in comparison to primary tumor cell lines." (PMID 32630254, 2020). "FN1 is considered to be a biomarker of epithelial–mesenchymal transition (EMT), which has been proposed as a key step for the behavior of tumor metastasis by allowing neoplastic epithelial cells to acquire a more mesenchymal phenotype." (PMID 30736807, 2019). "Accordingly, GALNT3/T6 KO-derived tumor tissues showed reduced staining intensity for all of GALNT6, FN1, and MUC1 when compared with the Ctrl and GALNT3 KO tissues." (PMID 31071912, 2019). "For instance, FN1 is highly expressed in a variety of tumor tissues including ESCC, which can promote tumor metastasis and invasion." (PMID 31235759, 2019). "We performed meta-analysis on 8 microarray studies and identified six significantly up- (PLAU, FN1, CDCA5) and down-regulated (CRNN, CLEC3B and DUOX1) genes which were subsequently quantified by RT-qPCR in 100 HNSCC patient margin and core tumour samples." (PMID 31443700, 2019). "In PDAC, early sequencing studies identified genetic alterations in the integrin signalling pathway (ITGA4, ITGA9, ITGA11, LAMA1, LAMA4, LAMA5, FN1 and ILK) in 67% of tumours." (PMID 31330086, 2019). "In comparison with the control group, except for miR-204-5p, the expression levels of ITGA2, FN1, ICAM1, CDH2, TIMP1, CLDN1, TNFRSF12A, miR-146b, and miR-222 were all up-regulated in the tumor group, consistent with the results of the bioinformatics analyses." (PMID 30414611, 2018). "Mesenchymal markers, including FN1 and vimentin (VIM), were overexpressed in tumor buds compared with IEC and CCPT, thus suggesting an EMT phenotype that was characteristic of the tumor bud cells." (PMID 28687755, 2017). "Our study indicates that the early stages [tumor, node, and metastasis (TNM) stage I and II] of HCC can be diagnosed using the combination of AFP and FN1 through a routine blood test." (PMID 28842594, 2017). "Many HBV integration events occurred near or within fragile sites and other repetitive regions, such as TERT, FN1, MLL4, ROCK1, CCNE1, SENP5, Alu sequences, and microsatellites, which are prone to tumor development and progression." (PMID 28382278, 2017). "FN1, SPP1, CXCL12 and vitronectin (VTN) are known to promote the survival and migration of tumor cells." (PMID 27329720, 2016). "This included EC-specific proteins (e.g. COL1A1, FBN1), tumour-specific proteins (e.g. ITGB1) and proteins up-regulated in both cell types (FN1, THSB1, CD44, ITGA4, CTGF)." (PMID 27049916, 2016).
tumor (continued). "While the increased expression of VCAM1 promotes tumor invasion and metastasis, high levels of VTN and/or FN1 in circulation have been reported to promote tumor formation and metastasis." (PMID 26930275, 2016). "This study highlights the significance of FN1 and SPP1 in the metastatic microenvironment based on the following evidences: First, the seeding and outgrowth of tumor cells were increased in the bleomycin-induced fibrotic lungs." (PMID 27329720, 2016). "Collectively, we suggest that the FN1/SPP1-ITGAV pathway plays an important role in the chemotaxis of tumor cell to fibrotic lungs and in the apoptosis resistance of seeding tumor cells in the lungs." (PMID 27329720, 2016). "BIRC3, CAV1, CAV2, FN1, ITGA1 and THBS1 were functionally enriched to focal adhesion, which contributes to antiangiogenic and anti-tumour effects." (PMID 27557147, 2016). "Proteomic analysis of MDCKYBX1 tumour xenografts revealed 428 proteins identified in MDCKYBX1 tumour xenografts, and EMT markers (VIM, FN1 and S100A4) and proteins involved in cancer progression (H-Ras and CLU) were identified." (PMID 25980435, 2015). "The most encouraging findings of our study is that metformin treatment led to decreased expression of several genes involved in tumor invasion and migration, including DCN, MMP7, FN1, and WFDC." (PMID 25909163, 2015). "Verification studies using qRT-PCR, immunoblot and IHC assays confirmed that the expressions of S100A2, POSTN, FN1 and KRT17 were, indeed, significantly increased in tumor tissues." (PMID 25874882, 2015). "These genes included tumor markers (MUC16), genes that control tumor migration (MYL9), metastasis (CEACAM6, VEGFC, CX3CL1, CST1, CCL5, S100A9, IGF1, NOTCH3), cell adhesion (FN1, CEACAM1), and inflammation (TRAF2, NF-κB2 and RelB)." (PMID 26090868, 2015). "Those genes reportedly involved in tumor cell adhesion, gap junction and ECM, such as CHD1, Cx26, Cx43, Cx45, COL1A1, FN1, LOX, ITGB1 and LAMA4, were also up-regulated following 3D cultures." (PMID 26055407, 2015). "In tumor-adjacent normal breast tissues, the expressions of CTGF were also examined to positively correlate with FN1 and VIM and negatively correlate with CDH1." (PMID 26318291, 2015). "In poorly metastatic tumors, fibronectin (FN1) and periostin (POSTN) are secreted by the tumor cells, whereas in highly metastatic tumors, they are secreted by both the tumor cells and the stromal cells." (PMID 24618895, 2014). "FN-1 also increases MMP9 activity, which together with urokinase is involved in tumor cell invasion through the extracellular matrix." (PMID 21062482, 2010). "In order to examine the mRNA expression of FN1 in RCC, 109 tumour RNA samples and corresponding histopathological normal renal tissue of 86 of these patients were analysed using quantitative real time PCR." (PMID 20860816, 2010). "Among the overexpressed genes in tumor, MMP1 showed the highest order of magnitude (510-fold) and FN1 the lowest (2.6-fold)." (PMID 19835631, 2009). "Furthermore, Cox’s regression analysis showed that FN1, VASP, and CEP63 were independent prognostic factors of tumour relapse." (PMID 40149716, 2025). "In addition, Metab-GS scores are positively correlated with protein expression of mesenchymal marker, FN1, and positively correlated with epithelial marker, E-cadherin suggesting that Metab-GS correlates with EMT-driven tumor progression." (PMID 40626022, 2025). "Furthermore, some studies have shown that FN1 and CCL5 gene expression positively correlates with immune cell infiltration within the tumor." (PMID 39245631, 2025). "FN1, as a core ECM component secreted by scPAS + cells, enhances scPAS + cell-vascular wall anchoring through “endothelial cell-tumor cell” adhesion bridge construction, reducing tumor cell detachment and apoptosis following TACE treatment." (PMID 41450464, 2025).
tumor (continued). "Here, we have shown that FN1 does not contribute to cell death, but that its overexpression in platelet-educated cancer cells reduces tumor cell migration." (PMID 40096084, 2025). "Concurrently, RT-qPCR analysis revealed that the expression levels of tumor proliferation markers (MCM2 and Ki-67) and epithelial-mesenchymal transition (EMT)-related markers (CDH2, VIM, and FN1) were also significantly elevated following TRPM6 knockdown, consistent with the phenotype assay results." (PMID 41562086, 2025). "Additionally, we observed that the expressions of the cell adhesion-related genes FN1 and LAMB1 were upregulated after PAQR3 knockdown, aligning with the biological function of PAQR3 as a tumor suppressor gene." (PMID 40723340, 2025). "On the other hand, C3 FN1+ TCs essentially did not go beyond node 1, while C2 SLC40A1+ TCs and C3 FN1+ TCs were primarily seen in the early phases of tumor development." (PMID 40612060, 2025). "Second, tumor subsets enriched for microenvironment features, including hypoxia markers (e.g., Slc2a1, Pdk1, Car9), extracellular matrix (ECM) genes (e.g., Matn2, Fn1, Dcn, Col6a1), vasculature (e.g., Cdh5, Pecam1, Vwf), and interferon response genes (e.g., Rsad2, Ifit3, Gbp3, Cxcl10, Cd274)." (PMID 40171265, 2025). "The dense expression of FN1 may serve as a barrier to intertumoral TLS localization, in agreement with significant anti-tumor immune responses, and may affect the efficacy of immunotherapy through interactions with ILT3." (PMID 40282505, 2025). "Together, FN1 and CD44 cooperatively regulate tumor progression and the immune microenvironment." (PMID 41514658, 2025). "Moreover, FN1 and RAP1B were also positively upregulated in PTCs from primary and metastatic colon cancer tumour tissues." (PMID 40638546, 2025). "We also suggest CAFs secreted CSF1 or FN1 could unidirectionally target cDC2, C1QC+TAMs, and SPP1+TAMs to promote macrophage or cDCs differentiation, as well as tumor development." (PMID 39323622, 2024). "Fibronectin 1 (FN1), an essential component of ECM has been found elevated expression in PC tissues and it can exert regulatory effects on ECM remodeling as well as tumor metastasis." (PMID 38581008, 2024). "The FN1–aVb1 and FN1–a5b1 pairs exhibited a high level of enrichment in the interaction between PTH1R+ pericytes and ECs, with FN1–aVb1 also showing significant enrichment between PTH1R+ pericytes and tumor cells." (PMID 39640361, 2024). "Additionally, CD34, FN1, LOXL2, and VCAN are key players in tumor angiogenesis, invasion, and metastasis." (PMID 39012409, 2024). "In addition, we also identified several key genes involved in tumor aggressiveness, including COL5A1, VEGFA, TNC, and FN1." (PMID 38390494, 2024). "Interestingly, the main tumor interaction networks include ECM components previously identified in the KEGG analysis (SPP1, FN1, collagens), cell–cell interactions and cholesterol along with apolipoprotein (adult)." (PMID 39482394, 2024). "The reduction in tumor weight could be secondary to decreased ECM accumulation, as reflected by the positive correlation between tumor weight and FN1 levels." (PMID 38994944, 2024). "Importantly, we found that CAFs overexpressing FN1 and POSTN significantly promoted the wound healing and invasion ability of tumor cells in vitro validation." (PMID 38601538, 2024). "Targeting FN1, COL1A1, or downstream signaling pathways may offer new therapeutic opportunities for inhibiting tumor growth and improving treatment responses." (PMID 39065771, 2024). "The THBS1 expression levels were significantly higher in the metastatic nodules in lungs and tumor nodules in the abdominal cavity of the FN1 3′-UTR overexpressed group than that of the negative control group." (PMID 37771777, 2023). "In addition, we found a significant increase in the expression of the fibrosis markers collagen type I alpha 1 chain (COL1A1, OMIM 120150) and fibronectin 1 (FN1, OMIM 135600) in the tumor tissues of the proband." (PMID 37752101, 2023).
tumor (continued). "In these human neoplasms, the macrophage signature correlated with the expression of SNA1, FN1, ACTA2 (αSMA), SPP1 (osteopontin), COL1A1, and VIM, all genes that are specific for active CAFs, indicating that this gene signature is associated with CAF activation." (PMID 37199012, 2023). "tRF-19-R118LOJX might play a crucial role in angiogenesis, tumor cell migration, invasion, and proliferation, and survival through the target genes COLA1, FN1, and MSN." (PMID 37864150, 2023). "High expression of FN1 mRNA and FN1 protein in ESCC tumor tissues was significantly correlated with the depth of tumor invasion, lymph node metastasis and clinical stage of the tumor (P < .05)." (PMID 37026938, 2023). "Notably, the presence of FN1 appears to profoundly influence various malignant biological factors, including the ECM and acquisition of epithelial‐like characteristics, in tumour cells." (PMID 37784253, 2023). "It is worth noting that tumor cells 3 cluster exhibited high expression of mesenchymal markers (ZEB1, FN1, and VIM) compared to the other two tumor cell clusters, suggesting that this population of cells may have undergone epithelial-mesenchymal transition." (PMID 37007745, 2023). "Consequently, we found that COX-2-mediated exo-miR-1290 improves CAFs activation and tumor progression by suppressing CUL3 expression and upregulating Nrf2 expression and Nrf2-mediated FAP-1 and FN1 transcription in fibroblasts." (PMID 37723559, 2023). "Silencing CD44 and FN1 in EO771 cells and MDA-MB-231 cells downregulated MTT-based viability as well as the expression of Lrp5, MMP9, Runx2, and Snail in EO771 cells, whereas their silencing significantly suppressed MSN-induced tumor inhibition." (PMID 34976221, 2022). "The FN1-EGF fusion, which has not been observed in any other neoplasm, appears to be the main driver of mutation in CAFs." (PMID 35309385, 2022). "Our observations from this study suggest that FN1 and THBS1 might have potential to serve as novel biomarkers for predicting NSCLC tumor response to radiotherapy." (PMID 36567906, 2022). "Unsupervised clustering on the expression profiles issued from this series suggested two distinct subgroups: one composed of various molecular subtypes including CSF1 and FN1 rearranged samples and one composed of four tumors harboring an HMGA2::NCOR2 fusion, suggesting distinct tumor entities." (PMID 36439507, 2022). "Expression of Fn1 and Col1a1 was significantly higher in tumor-bearing bones vs. non-tumor-bearing bones." (PMID 35565211, 2022). "Firstly, tumor cells secrete Tsp2 to induce the transformation of normal fibroblasts to TAFs, and TAFs remodel the extracellular matrix by secreting COL1A1, COL1A2, COL5A1, FN1, and VCAN." (PMID 35982904, 2022). "Among the top enriched signaling pathway network, the interactions between THBS2+ CAFs and other cells within the tumor micro-ecosystem were most mediated by THBS, followed by stromal/immune signaling pathways, e.g. THY-1, FN-1, TGF-β, IL6/4, MHC-I, VEGF, CD40, or TIGIT." (PMID 35547750, 2022). "Collectively, these data suggested that HOXD11 might induce FN1 transcription by participating in ECM-mediated EMT and promoting tumor metastasis in PSCC." (PMID 36151071, 2022). "On the other hand, COL1A2, COL3A1, COL5A1, FN1, and SPARC may be more involved in tumor progression from stage 1 to stage 2, at which the tumor cells gain the ability to invade surrounding tissues." (PMID 35739492, 2022). "In addition, Tumor IMmune Estimation Resource (TIMER), cBioPortal, and immunohistochemical studies were performed to explore the relationship of FN1 and different immune-related cells in tumor microenvironments." (PMID 36081567, 2022). "Furthermore, a comprehensive database analysis showed that FN1 had a high expression level between HNSCC patients with post-operative radiation therapy failure and tumor tissues of HNSCC from the GEO and TCGA." (PMID 36212151, 2022).
tumor (continued). "Furthermore, we evaluated the possible link between the ECMGs and the tumor stage of PAAD, and 8 ECMGs (i.e. FN1, LAMA3, ITGB6, ITGB4, ITGA2, LAMC2, COL11A1, LAMB3) were detected to be significantly associated with tumor stage." (PMID 36311789, 2022). "Although FN1 has been demonstrated to exert essential roles in tumorigenesis and tumor progression, the clinical prognostic value and biological function of FN1 have never been illustrated." (PMID 36035176, 2022). "FN1, APOA1, CXCL8, MMP1, MMP3, and THBS1 were significantly upregulated in the tumor samples." (PMID 35719376, 2022). "Interestingly, TR Mac.3 exhibited extremely high expression of M2 and phagocytotic signatures, and showed pathway activations similar to those of the pro-tumor TAM clusters (i.e., FN1+ TAM)." (PMID 36423636, 2022). "Fibronectin 1 (FN1) was identified to interact with Fam20C and promote tumor cell migration." (PMID 34988120, 2021). "The addition of stromal cells increased transcription of matrix remodelling proteins FN1 and MMP9, induced release of tumour-promoting immune molecules MIF, Serpin E1, CXCL1, IL-8 and CXCL12 and altered cancer cell expression of immunotherapeutic targets EGFR, CD47 and PD-L1." (PMID 34885111, 2021). "In addition, miR-765 mimics obviously down-regulated the expression of several EMT-related markers (e.g., COL3A1, FN1, CDH2, S100A4, MMP9, SNAIL and ZEB1) and up-regulated TJP1 expression in tumor lesions." (PMID 33859750, 2021). "The PPI network also reveals that proteins were related with cell adhesion of the ECM remodeling pathway (DCN, FN1 etc.), suggesting that VCAN may be involved in tumor progression which is an important ECM component through the ECM remodeling pathway." (PMID 33604385, 2021). "HBV integrations within the FN1 gene have been reported mostly in non-tumor samples, and it has been found that the gene is downregulated in tumor samples." (PMID 34442866, 2021). "Analysis of bulk tumour mRNA displayed a strong correlation between ACTA2, a marker of MSCs, and matrix remodelling enzymes (MMP2), ECM proteins (VCAN, FN1, COL1A1), immunomodulatory molecules (Serpine1, CXCL12), innate immune cell markers (CD14, ITGAX) and adaptive immune cell markers (CD4)." (PMID 34885111, 2021). "C3, FN1, and C3AR1 are overexpressed in multiple tumor cell lines." (PMID 34688260, 2021). "It suggested that CAFs and EMT-related genes, the high expressions of FN1, ZEB1 and TCF4 in the tumor microenvironment may be involved in TCM syndromes classification in CRC." (PMID 34876190, 2021). "BD treatment may induce ANXA2, TGFI, FN1, HSP90B1 down-regulation, and FRK up-regulation to inhibit tumor metastasis by regulating autophagy, hypoxia, β-catenin, and STAT3 signaling pathways." (PMID 34685653, 2021). "Furthermore, we divided the tumor sites into two groups according to FN1 expression and found that CD276 levels were positively correlated with the level of FN1(P < 0.05)." (PMID 35141255, 2021). "Furthermore, FN1, TNC, and TGFBI have been reported to promote tumor migration, invasion, and adhesion, which are functions facilitating metastatic spread." (PMID 32312959, 2020). "Heterogeneous tumours containing WM266‐4 FN‐kd showed delayed tumour growth onset, indicating that FN1 is also important for growth in heterogeneous tumours, which was also reflected in tumour‐free survival." (PMID 32145051, 2020). "These secreted proteins were transforming growth factor beta induced (TGFBI), tenascin C (TNC), and fibronectin (FN1), which have in common that they are ECM proteins and as such may provide support for tumor cell adhesion and migration." (PMID 32312959, 2020).